CYP19A1 (cytochrome P450 family 19 subfamily A member 1)
Diseases named in the same sentence as CYP19A1 in open-access papers (continued):
Sharing a sentence is not in itself a finding about the gene and the disease.
esophageal cancer (1 paper, 2020). A primary or metastatic malignant neoplasm involving the esophagus. "Out of 12 SNPs, two SNPs rs12190287 of TCF21 and rs10046 of CYP19A1 were significantly associated with esophageal cancer with Odds Ratio (OR) 1.412 (1.09–1.8 at 95% CI, p = 0.008) and 1.54 (1.21–2.072 at 95% CI, p = 0.0007) within the population of Jammu and Kashmir." (PMID 32487238, 2020).
Glucose intolerance (1 paper, 2017). Glucose intolerance (GI) can be defined as dysglycemia that comprises both prediabetes and diabetes. "Treatment of wild type mice with paroxetine, a chemical inhibitor of SERT, also resulted in Cyp19a1 suppression, decreased circulating 17β-estradiol levels, abnormal fat accumulation, and glucose intolerance." (PMID 28442777, 2017).
Hepatitis (1 paper, 2024). Inflammation of the liver. "Macromolecular target prediction using the SwissTargetPrediction indicated that these molecules could also target enzymes associated with metabolic diseases (HSD11B1), could be aromatase inhibitors (CYP19A1), and exhibited anti-hepatitis and antihyperthyroidism (SHBG) activities, among others." (PMID 38675469, 2024).
hyperthyroidism (1 paper, 2020). Overactivity of the thyroid gland resulting in overproduction of thyroid hormone and increased metabolic rate. "It has been shown that the hyperthyroidism in zebrafish larvae inhibited the aromatase (cyp19a1) activity, leading skewed sex ratio in favour of males." (PMID 32492950, 2020).
Hypoglycemia (1 paper, 2025). A decreased concentration of glucose in the blood. "The present study investigated the corollary hypothesis that VMNdm Ghrh neurons express CYP19A1, the gene that encodes CYP19A1 protein, and that eu- and/or hypoglycemia-associated transcription of this gene may be affected by age in one or both sexes." (PMID 40613376, 2025). "Results also show that VMN Ghrh gene silencing increased proportional CYP19A1 gene transcription V- or INS-injected old and young female rats, and that in contrast to old male rats, hypoglycemia up-regulated this relative expression ratio in old females." (PMID 40613376, 2025).
hypospadias (1 paper, 2020). Hypospadias is the displacement of the urethral meatus on the ventrum of the penis. "In conclusion, our study demonstrated that disrupted AR and CYP19A1 expression could play a causative role in the development of hypospadias." (PMID 32515122, 2020). "AR and CYP19A1 were significantly decreased in severe and mild hypospadias." (PMID 32515122, 2020). "In conclusion, our findings demonstrated that dysregulation of AR and CYP19A1 could play a crucial role in the development of hypospadias." (PMID 32515122, 2020). "Importantly, compared to mild hypospadias, AR and CYP19A1 showed lower expressed in severe hypospadias, whereas not reaching statistical significance in our panel." (PMID 32515122, 2020).
Iron deficiency (1 paper, 2025). "Iron deficiency arrested mouse estrous cycles at diestrus, blocked secondary follicular development and ovulation due to reduced ovarian ATP levels, downregulation of follicular development markers (FSHR, CYP19A1, CCND2), and decreased estradiol—17β (E2) compared to controls." (PMID 41169787, 2025).
leprosy (1 paper, 2015). Leprosy is a chronic infectious disease affecting primarily the skin and peripheral nervous system. "The NFKβ1, CASP8, PAR1 and IL4 INDELs were associated with leprosy susceptibility, while NFKβ1, CASP8, PAR1 and CYP19A1 were associated with the MB (Multibacilary) clinical form of leprosy." (PMID 26367014, 2015). "NFKβ1 [rs28362491], CASP8 [rs3834129], PAR1 [rs11267092] and IL4 [rs79071878] genes are potential markers for susceptibility to leprosy development, while the INDELs in NFKβ1, CASP8, PAR1 and CYP19A1 (rs11575899) are potential markers for the severe clinical form MB." (PMID 26367014, 2015). "We investigated the possible effects of CYP19A1 [rs11575899], NFKβ1 [rs28362491], IL1α [rs3783553], CASP8 [rs3834129], UGT1A1 [rs8175347], PAR1 [rs11267092], CYP2E1 [INDEL 96pb] and IL4 [rs79071878] genes in a group of 141 leprosy patients and 180 healthy individuals." (PMID 26367014, 2015).
liver cancer (1 paper, 2024). An epithelial or non-epithelial malignant neoplasm that arises from the liver. "Statistically significant variations (p < 0.05) were observed in the expression levels of CYP3A, ESR1, and CYP19A1 across different stages of liver cancer." (PMID 39204124, 2024). "The stage plot analysis further highlights the dynamic nature of these genes across different cancer stages, particularly in liver cancer, where CYP3A4, ESR1, and CYP19A1 showed significant changes." (PMID 39204124, 2024).
liver fibrosis (1 paper, 2021). "In addition, among all common targets for RGGs and liver fibrosis, ESR1, ESR2, AR, ACHE, CYP19A1, and AKR1B1 have a high degree of interaction with other targets and some active compounds." (PMID 35115923, 2021).
lymph node metastasis (1 paper, 2018). "For 17 of these patients, one lymph node metastasis each was also analyzed, which exhibited 1.5-fold lower mean CYP19A1 levels than their matched primary tumors; however, this difference was not significant (P = 0.113)." (PMID 29363090, 2018).
lymphoma (1 paper, 2008). A malignant (clonal) proliferation of B- lymphocytes or T- lymphocytes which involves the lymph nodes, bone marrow and/or extranodal sites. "Four additional CYP19A1 SNPs, rs10046 (3′UTR, 1678T>C), rs2289105 (IVS7−79T>C), rs2899472 (IVS4−1334C>A), rs9944225 (IVS3+7029C>A) and rs4774584 (IVS1−26860G>A) influenced SLL/CLL risk and rs2008691 (IVS1−13201A>G) was positively associated with the group of “other” lymphoma subtypes." (PMID 18636124, 2008).
mesothelioma (1 paper, 2021). A usually malignant and aggressive neoplasm of the mesothelium which is often associated with exposure to asbestos. "The quantization of COX-2 and CYP19A1 mRNA in five mesothelioma cell lines (MPP89, Ist Mes2, Ist Mes1, MSTO and NCI) by RT-PCR revealed that Ist Mes-1, Ist Mes-2, and MPP89 cell lines endowed higher mRNA COX-2 levels and exhibited higher mRNA CYP19A1 levels." (PMID 34404424, 2021).
migraine (1 paper, 2012). "We strongly suggest CYP19A1 polymorphisms to be the major contributing factors in migraine susceptibility instead of genetic variants of estrogen receptors." (PMID 22511967, 2012). "Haplotype analysis of CYP19A1 polymorphisms revealed the significant predominance of two haplotype groups in migraine patients." (PMID 22511967, 2012). "In future, more studies in other ethnic groups should focus on CYP19A1 polymorphisms to better understand the pathobiology of migraine." (PMID 22511967, 2012). "Hence, we conclude that CYP19A1 polymorphisms and haplotypes are the major causal factors for migraine susceptibility." (PMID 22511967, 2012). "Our data indicates strong association of CYP19A1 3′UTR polymorphisms with migraine susceptibility." (PMID 22511967, 2012). "It implies the role of CYP19A1 polymorphisms in defining the effect on migraine susceptibility." (PMID 22511967, 2012). "Significant interactions were observed for CYP19A1 rs10046 with ESR2 rs1271572, ESR1 rs2234693 and ESR1 rs9340799 polymorphisms conferring risk for migraine susceptibility." (PMID 22511967, 2012). "In conclusion, we report the significant association of CYP19A1 3′UTR and ESR1 rs2234693 polymorphism with migraine risk." (PMID 22511967, 2012). "Based on these findings, we suggest CYP19A1 polymorphisms to be the major contributing factor in migraine susceptibility rather than ESR1and ESR2 polymorphisms as shown by interactions of genotypes and haplotypes." (PMID 22511967, 2012).
mucinous carcinomas (1 paper, 2021). "Among EldCa, mucinous carcinomas exhibited significantly higher levels of CYP19A1 mRNA than in other carcinomas." (PMID 34133482, 2021).
myopia (1 paper, 2011). "An MDR analysis corroborated the synergistic genotype association and demonstrated that synergistic interaction between rs6203 (HSD3B1), rs10046 (CYP19A1), and sex might confer susceptibility to high myopia (p=0.019)." (PMID 21921981, 2011). "We observed associations between certain combinations of polymorphisms at steroidogenesis enzyme genes (rs6203 [HSD3B1], rs10046 [CYP19A1], and sex) and high-myopia risk; meanwhile, there is evidence of correlations between rs605059 (HSD17B1)–sex interaction and sex hormone levels." (PMID 21921981, 2011).
osteoarthritis (1 paper, 2024). A noninflammatory degenerative joint disease occurring chiefly in older persons, characterized by degeneration of the articular cartilage, hypertrophy of bone at the margins and changes in the synovial membrane. "For the 8 gene loci ESR1 rs2234693, CYP19A1 rs700518, ADAM12 rs3740199, ACE I/D rs4340, VDRrs731236, TGF-β rs1982073, FAS rs1800682, ADAMTS5 rs226794, the cumulative sample sizes were deemed sufficient to conclude that they are not correlated with osteoarthritis." (PMID 39248710, 2024).
prostate adenocarcinoma (1 paper, 2021). "The mean expression level of the CYP19A1 gene was significantly higher in HeyLHigh prostate adenocarcinoma samples than in HeyLLow prostate adenocarcinoma samples." (PMID 35096586, 2021).
prostate tumor (1 paper, 2017). "In this sense we found that CYP19A1 was present in the CTC population of our mCRPC patients suggesting that patients progressing after androgen deprivation could present adaptative mechanisms to maintain the hormone stimulation of prostate tumor cells." (PMID 28903376, 2017).
tongue cancer (1 paper, 2021). A malignant neoplasm affecting the tongue. "The results of log-rank test demonstrated that PGK1, CYP19A1, PFKM, and ZC3H12D were associated with the OS in tongue cancer patients." (PMID 33758601, 2021). "Previous studies have reported that the expression of LEPR 42, PFKM 43, 44, PGK1 45, 46, CYP19A1 47, 48, SLC20A1 49, and ZC3H12D 50 were associated with tumorigenesis and progression in various tumor types, which support the further identification and exploring in tongue cancer." (PMID 33758601, 2021). "PGK1, SLC20A1, LEPR, CYP19A1, ZC3H12D, and PFKM were found to be independent predictors in tongue cancer." (PMID 33758601, 2021).
Turner syndrome (1 paper, 2024). Turner syndrome is a chromosomal disorder associated with the complete or partial absence of an X chromosome. "When attempting to replicate the differentiation process of embryonic granulosa cells, we observed the downregulation of specific genes—GATA4, FOXL2, AMHR2, CYP19A1, and FSH—in Turner syndrome-derived granulosa cells (TS-GCs)." (PMID 39543104, 2024).
uterine leiomyosarcoma (1 paper, 2015). "Both SF-1 and CYP19A1 genes were expressed in the tumor, and expression levels of these genes were markedly higher in the tumor than in uterine leiomyosarcoma." (PMID 26576867, 2015).
tumor (65 papers, 2009 to 2026). "It is also very important to note that intratumoral levels of CYP19A1 demonstrate a significant association with ER expression and tumor grade." (PMID 27783191, 2017). "Interestingly, tamoxifen up-regulates CYP19A1 expression through GPER not only in tumor cells themselves but also in cancer-associated fibroblasts (CAFs) from the tumor microenvironment." (PMID 41141392, 2026). "On the basis of the results of differential expression analysis and analysis for risk factors, we selected the gene CYP19A1 as our target gene which exhibited the highest relative expression in tumor tissues and demonstrated the most obvious correlation with the worse survival prognosis." (PMID 37784135, 2023). "Aromatase (CYP19A1): Aromatase is an enzyme responsible for the conversion of androgens into estrogens, contributing to the establishment of a tumor-promoting microenvironment." (PMID 41438588, 2026). "Our in vitro and in vivo studies demonstrate that CYP19A1 promotes malignant biological behaviors, including tumor proliferation, invasion, and migration, as well as platelet activation in vitro." (PMID 39457539, 2024). "Subsequent analysis of the TCGA-COAD dataset revealed significantly elevated expression of CYP19A1 in tumor tissues compared to adjacent non-tumor tissues (p < 0.05)." (PMID 39457539, 2024). "To confirm the oncogenic role of CYP19A1 in vivo, we developed a subcutaneous xenograft tumor model in nude mice and observed that CYP19A1 knockdown markedly suppressed subcutaneous tumor growth." (PMID 39457539, 2024). "Subsequently, CYP19A1 immunohistochemistry was performed on a tissue microarray comprising 96 tumor samples from patients with CRC." (PMID 39457539, 2024). "Tumor weight in the CYP19A1 knockdown group was significantly reduced compared to the control group." (PMID 39457539, 2024). "The 96 paired tissue samples showed that the CYP19A1 expression level was significantly higher in tumor tissues and metastatic lymph nodes compared to the pericancerous tissues (p < 0.001)." (PMID 37047797, 2023). "Unsurprisingly, CYP19A1 inhibition by the letrozole or siRNA in tumors increased the proportion of 7-AAD+ tumor cells after co-culture with PBMCs (1.5- and 2-fold, respectively)." (PMID 37055842, 2023). "We observed an apparent colocalization of CYP19A1 with CK (tumor cell marker), indicating that CYP19A1 is mainly expressed in tumor cells." (PMID 37055842, 2023). "KM plotter Pan-cancer RNA-seq was used to analyze correlation of aromatase (CYP19A1) mRNA expression and survival in different available tumor types." (PMID 36989252, 2023). "Multiplex immunofluorescence analyses revealed that CYP19A1 protein expression was negatively correlated with CD8+ T cell infiltration, but positively correlated with the levels of tumor-associated macrophages, CAFs and endothelial cells." (PMID 37055842, 2023). "The key enzyme of estrogen biosynthesis after menopause is aromatase (CYP19A1, Cytochrome P450 Family 19 Subfamily A Member 1), an enzyme complex found in both breast adipose tissue and tumor tissue." (PMID 36555323, 2022). "The primary mediator of postmenopausal estrogen biosynthesis is aromatase (also known as CYP19A1, Cytochrome P450 Family 19 Subfamily A Member 1), an enzymatic complex found both in breast adipose and tumor tissues." (PMID 34485137, 2021). "CYP19A1 mRNA expression was positively correlated with tumor size (r = 0.49; P < .05), whereas expression of ESR1 (ERα) mRNA was negatively associated with this variable (r = –0.54; P = .0296)." (PMID 31853538, 2020). "In case 2, assessing the gene expression levels for SF-1 and CYP19A1 in the tumor by RT-qPCR showed that they were consistent with the results of immunohistochemical studies; both SF-1 and CYP19A1 genes were expressed in the tumor." (PMID 26576867, 2015).
tumor (continued). "Our study has advanced our understanding of CYP19A1 by suggesting that the modulation of aromatase activity by either germ-line variation or pharmacological agents can influence the development of ER+ tumour in postmenopausal women." (PMID 20617168, 2010). "The analysis showed that CYP19A1 had higher expression in tumor tissue than in normal tissue." (PMID 41050076, 2025). "Future studies should focus on validating our findings in preclinical animal models of CRC to assess the therapeutic potential of targeting the CYP19A1/estrogen/complex I axis and evaluate the impact of CYP19A1 modulation on tumor growth, metastasis, and chemotherapy response." (PMID 39468645, 2024). "Additionally, the CYP19A1 siRNA remarkably inhibited PD-L1 expression on tumor cells, induced vascular normalization, as manifested by an obvious decrease in the hypoxia-inducible factor (HIF) -1α level and an increase in CD31+ αSMA+ cells number." (PMID 37055842, 2023). "Moreover, our results indicate that GSE is a potentially effective SCD1 inhibitor that prevents lipid accumulation and blocks tumor cell invasion and migration via decreasing CYP19A1 expression and estrogen synthesis." (PMID 37047797, 2023). "CYP19A1 may promote the occurrence and progression of tumours via oestrogen metabolism enzymes and then affect inflammatory pathways." (PMID 38045683, 2023). "GCT are functional tumors that may produce excessive levels of E2 either because of the up-regulation of CYP19A1 expression or the high number of tumor cells producing E2." (PMID 35008938, 2022). "Furthermore, CYP19A1 expression and aromatase activity has been reported in tumor-infiltrating lymphocytes." (PMID 35573990, 2022). "No other associations were observed between the relative expression of CYP19A1 mRNA and the other variables studied, such as age, use of tobacco, menopausal status, grade, nodal status (N), tumor stage, estrogen and progesterone receptor, HER2 and histological type." (PMID 32460723, 2020). "CYP19A1 mRNA expression levels were also determined for these 15 cell lines and 100 tumor samples." (PMID 29363090, 2018). "Recent studies exploring the association between enzyme levels and tumor characteristics found a correlation between STS with tumor grade and lymphovascular invasion and described an association between high CYP19A1 or 17βHSD1 and poor patient prognosis." (PMID 30283331, 2018). "Finally, in the other patient cohort from TCGA, CYP19A1 was expressed higher in the tumor compared to that in normal counterparts, and also promoted progression." (PMID 27893427, 2017). "In addition, we examined CYP19A1 protein expression and the intratumoural E2 concentration in lung lesions of KO-NC and KO-METTL3 tumours in the tail-vein injection model, and the results showed that CYP19A1 protein and E2 levels were significantly decreased after METTL3 knockout." (PMID 38238831, 2024). "Analyses of key target genes involved in the tumor–bone vicious cycle showed similar patterns of gene expression in the vehicle-treated Cont-4T1 and Pth1rKD-4T1 tumors except for Il6, Ackr3 (encoding CXCR7), and Cyp19a1, which were reduced in the Pth1rKD-4T1 cells." (PMID 36692956, 2023). "Indeed, in CRPC Cyp19a1 expression was significantly increased in tumor samples." (PMID 33451122, 2021). "The single-cell dataset showed significant under-expression of ADH1B, ADH4, CYP19A1, and GPX3 in tumor samples." (PMID 41031088, 2025). "Bioinformatics analysis revealed that APOA1, BCHE, and STARD5 were significantly expressed in normal samples, while CYP19A1 and PLA1A were considerably expressed in tumor samples in the TCGA-STAD cohort." (PMID 38357546, 2024). "We detected obvious decreases in CYP19A1 protein expression and estradiol production in siCYP19A1-treated MC38 tumor as compared with the si-Scram." (PMID 37055842, 2023).